STAT1 (signal transducer and activator of transcription 1)
Diseases named in the same sentence as STAT1 in open-access papers (continued):
Sharing a sentence is not in itself a finding about the gene and the disease.
infection (continued). "Thus, CD4 effector and regulatory subsets are variably affected in STAT1 GOF patients, however it remains unclear if this variability reflects specific STAT1 GOF mutation impacts and/or environmental influences such as infections or immunosuppressive treatments." (PMID 37275873, 2023). "On the other hand, infection with type I strain RH, type II strain PRU, and type III strain CL14 can induce the degradation of phosphorylated STAT1 in the nucleus of host cells." (PMID 38003154, 2023). "Although transcriptional complexes containing unphosphorylated STAT1 can mediate baseline expression of IFN-stimulated genes (ISG), canonical infection-induced STAT1-mediated ISG expression involves a phosphorylation cascade following IFN receptor ligation." (PMID 37275873, 2023). "Later in the infection, a GRA protein (TgIST) forms a high molecular weight complex inhibiting the STAT1 pathway that helps clear the parasite." (PMID 37646522, 2023). "In HCG4 overexpressed cells, SH/2014 infection increased the expression of RIG-I, p-IRF3, and p-STAT1/2, and the IFN-β level was also significantly increased compared to that in the control cells." (PMID 38274760, 2023). "The transcription levels of various signaling molecules, including IKKβ, p38, STAT1, STAT3, and STAT6, showed a sharp increase from day 6 after infection in HVEM−/− mice, compared with the rapid decrease at the same time in WT C57BL/6 mice." (PMID 35632787, 2022). "Meanwhile, we also found that 1,25(OH)2D3 reduced p-NF-κB, p-STAT1, and p-STAT3 protein levels induced by PEDV at 24 h post-infection." (PMID 36142545, 2022). "The transcriptions of IRF9 and STAT1 were increased markedly in the late stage of FJzz1 infection and the promotion of the phosphorylation and nuclear translocation of STAT1, implicating the activation of the JAK-STAT signaling pathway during FJzz1 infection." (PMID 35958569, 2022). "Significant differences (p < 0.05) in the expression of only STAT1, STAT4, TRAF6, and NFKB1 factors were observed for the different types of macrophages, at different times of infection." (PMID 35774406, 2022). "To compare the effects of lncRNA-155 and miRD-lncR155 on virus-induced activation of STAT1, we further examined the activation of STAT1 in miRD-lncR155- or full length lncRNA155-overexpressed 293T cells after WSN infection." (PMID 36321836, 2022). "We found cytokines like IFNγ, IL-4, IL-13, IFNβ1, TNFα, and transcriptional regulators such as HIF1α, STAT1, CTCF, TP73, IRF1, MXD1, ATF4, SPI1 mediate macrophage activation upon infection." (PMID 35789215, 2022). "In parallel with the induction of STAT1 expression, transcription of some IFN stimulated genes (ISGs) was also noticed upon USUV infection of JAR cells, such as OAS2 and ISG15." (PMID 35893684, 2022). "In previous STAT1 GOF studies, high rates of bacterial (74%) and viral (38%) infection were detected, with common viral infectious agents being HSV, varicella-zoster virus, CMV, and EBV." (PMID 36225936, 2022). "Here, we found that both colonic and ileal networks generated with CARNIVAL shared similar transcription factors, including ATF2/3, FOS, JUN, STAT1, and NFKB1, which were all upregulated in both tissues upon infection." (PMID 35501398, 2022). "During the acute infection phase, SARS-CoV-2 can inhibit signal transducer and activator of transcription 1 (STAT1), elevating a compensatory hyperactivation of STAT3 that results in hypercytokinemia." (PMID 35897696, 2022). "JAK/STAT1 is activated by IFN-γ and plays a central role in Mφ differentiation, maturation, and host defense against pathogen infection." (PMID 36532054, 2022). "We investigated downstream targets of interferon signaling, including STAT1, STAT2, pSTAT1 and 2, and IRF1, 7 and 9 by flow cytometry in 30 patients with COVID‐19, 17 with mild, and 13 with severe infection." (PMID 34676541, 2022).
infection (continued). "STAT1 plays an essential role in the TLR-mediated antibody response of the marginal zone during inflammation and infection." (PMID 35563088, 2022). "Altogether, we conclude that despite the divergent efficacy of IFN-β induction by RSV and IAV, upon infection with any of these viruses, IFN-β is the main activator of STAT1 and STAT2 signaling." (PMID 36326278, 2022). "This was the case for the type I IFN response, but also for RIPK1, STAT1, DDX58, ISG15, TRIM25, and MYD88, involved in TNF-, TLR-, RLR-, and NFκB signaling, 48 h after MOPV infection." (PMID 35337059, 2022). "Similar to STAT1-/- or IFNAR1-/- mice, STAT2-/- mice display excessive inflammation, viral burden, and increased morbidity after infection with influenza virus." (PMID 36148221, 2022). "Next, we analyzed the total expression levels of STAT1 and STAT2 in mock or ASFV infected PAM that were either mock treated or treated with IFN-I at 7 or 15 h post-infection." (PMID 34512601, 2021). "Surprisingly, we also found that duck STAT1, a key regulator of ISGs, was increased 3.25-fold during DTMUV infection, indicating that DTMUV probably induce ISGs expression via the activation of canonical JAK-STAT pathway." (PMID 34335626, 2021). "Our previous results also indicated that STAT1 and STAT3 play critical roles in the regulation of UPEC invasion and infection in uroepithelial cells, especially those pretreated with glucose." (PMID 34946023, 2021). "We also examined STAT1 activation, which occurs downstream of IFNAR engagement, and found strong phosphorylation at 4-, and 6h post-infection, with peak activity at 4h." (PMID 34473814, 2021). "Out of the four Jak-STAT signaling molecules (suppressor of cytokine signaling 1 [SOCS1], SOCS3, STAT1, and STAT4) analyzed in this study, only the STAT1 gene was significantly upregulated (36 to 48 hpi) in ALI-PRECs following infection with PHEV." (PMID 34935443, 2021). "Remarkably, we also show that infection with both virulent and attenuated ASFV strains results in impaired expression of full-length STAT1." (PMID 34512601, 2021). "Herein, there was a significant increase in the expression of phosphorylated STAT1 and STAT3 in mouse lungs after H9N2 infection." (PMID 33968006, 2021). "STAT1 and STAT3 phosphorylation occurred consistently in Vero cells during the mock infection culture as we expected." (PMID 34835005, 2021). "In the experimental model of T-cell exhaustion induced by infection with Lymphocytic Choriomeningitis Virus, exhausted CD4+ T cells are subjected to ongoing chronic STAT1 activation and a desensitization of IFN-γ pathway." (PMID 34061845, 2021). "Consistent with earlier ISG mRNA induction during infection, SARS-CoV-2 infection promoted phosphorylation of STAT1 in Calu-3 cells, as recently reported." (PMID 33811184, 2021). "Infection of ferrets with SARS-CoV, after giving alpha2b interferon (IFN-α2b), indicated a predominant role of STAT1 in regard to the immune response." (PMID 33468694, 2021). "In Vero cells, STAT1 and STAT3 phosphorylation level similarly increased until 24 h culture in medium containing 2% FBS after mock-infection and HCoV-OC43 infection." (PMID 34835005, 2021). "This is evident, as phosphorylation of STAT1(Y701), downstream of the type I/III IFN receptors, was induced upon PVSRIPO infection." (PMID 33849973, 2021). "Our data suggest that YTHDF3 depletion affects the host cell response to PVSRIPO infection at a step between type I/III IFN release and p-STAT1(Y701) induction, which points to a defect in IFN-dependent JAK/STAT1 pathway activation." (PMID 33849973, 2021). "In T3M4 cells, with active baseline STAT1 signaling, YTHDF3 depletion diminished innate activation at 0 to 8 hpi, during the critical early phase of PVSRIPO infection." (PMID 33849973, 2021).
infection (continued). "GSK3β signaling promoted by infection, activated NF-κB-mediated expression of proinflammatory molecules and inhibited the activity of β-catenin, Nrf2, CREB, STAT1/3, and cJun-AP1, except in MCF7 and MDA-MB-231 stimulated with LPS." (PMID 34017345, 2021). "We inoculated six Stat1-/- mice with 106 plaque forming units (PFU) of CR6 intracranially (IC) and collected tissue and stool samples from three mice at 3 days post-infection (dpi), then from the remaining mice either at time of death or up to 30 dpi." (PMID 33705489, 2021). "The upregulation of IFITM3, STAT1, STAT2, PLSCR1, and NMI after infection was validated using western blotting and qRT-PCR." (PMID 34818332, 2021). "Deciphering the effects of YTHDF3 depletion on the innate host response to PVSRIPO infection indicated that the YTHDF proteins act at a step after IFN-β/IFN-λ1 release, implicating YTHDF3 as a mediator of JAK/STAT1 signaling." (PMID 33849973, 2021). "Protein expression levels of STAT1, pSTAT1, IRF-1, and pSTAT3 increased in WT mice during the course of infection." (PMID 33753412, 2021). "We previously showed that glucose can enhance UPEC-induced infection in uroepithelial cells via TLR-4 and JAK/STAT1 signaling pathways." (PMID 34946023, 2021). "WT and STAT1−/− HFF-1 cells were treated with α-NF, followed by infection with GFP-expressing HSV-1." (PMID 34668726, 2021). "We observed a trending increase in the levels of IFNAR1 and STAT1 following IFN-β treatment, similar to our findings in the adult brain following infection." (PMID 32457247, 2020). "RIG-I activation by 5′ppp-RNA stimulates the production of IFNβ from lung epithelial cells to the same extent as monocytic cells, albeit very late after infection at 48–72 h, through IRF3 and STAT1 activation." (PMID 32541772, 2020). "Transcription factor enrichment analysis unambiguously identified STAT1 and STAT2 binding sites as highly enriched in the promoter region of genes whose levels of expression were significantly regulated following infection of human intestinal organoids." (PMID 32184238, 2020). "In the present study, we similarly found that the expression of STAT1, IL8L1, and IL8L2 was increased in DF-1 cells after infection with IBDV." (PMID 31865850, 2020). "To determine the role of IFN signaling in SeV infection, we infected U3A cells (STAT1-defective cells derived from HT1080 parental cells) with SeV and compared the numbers of SeV RNA copies produced up to 36 h after infection." (PMID 32295917, 2020). "After infection with HMPV for 24 h, BEAS2b cells were treated with IFN to induce phosphorylation and nuclear translocation of STAT1 and STAT2." (PMID 32635475, 2020). "We observed a strong inflammatory gene signature in isolated monocytes during subpatent infection, including increased CXCL10, CXCL9 and STAT1 gene expression." (PMID 32566226, 2020). "Changes in gene expression in the brains of infected animals is minimal at 2- and 4-days post infection with moderate increases in Interferon-inducible CXCL10, CXCL11, B2m, and STAT1, as well as pro-inflammatory TNF, IL-1b and C3." (PMID 32133008, 2020). "Nevertheless, the infected fish at 15°C showed overexpression of STAT1, MHCII, CD4, IgT, and IgM transcripts, suggesting that the infection triggered a CD4+ T-cells response and a humoral response." (PMID 32695119, 2020). "Infection by SARS-CoV-2 delivers into cells NSP1 and ORF6, which efficiently inhibit STAT1 function that in turn increases STAT3 activity." (PMID 33379366, 2020). "Conversely STAT1, phosphorylated in M1-polarised macrophages exposed to LPS plus IFN-γ, was almost unaffected by KSHV-infection." (PMID 32418990, 2020). "Compared to infection with the parental virus, rFCV 2280-F9 p30 infection displayed attenuated activities in reducing the level of IFNAR1 and inhibiting the phosphorylation of STAT1 and STAT2, whereas rFCV F9-2280 p30 displayed enhanced activities." (PMID 33075108, 2020).
infection (continued). "Both, GMCSF- and FLT3L-BMDCs responded to mOVA2 infection with type I IFN activation signatures, e.g. induction of p-STAT1(Y701), STAT1, TAP1 and ISG15." (PMID 31988324, 2020). "IL-17-related infection scores are higher in SLT patients than both control groups; moreover, the clinical phenotype of SLT patients is similar to patients with STAT1 and STAT3-mediated IL-17 defects." (PMID 32868758, 2020). "Our work shows that infected fish at 15°C presented the overexpression of STAT1, MHCII, CD4, IgT, and IgM transcripts, suggesting that the infection triggered a CD4+ T-cells response and a humoral response." (PMID 32695119, 2020). "Following infection, IFN-β mRNA was transiently increased in the spleen of WT, STAT1 KO and STAT1/RAG1 DKO mice on day 3 postinfection and was undetectable at day 7 postinfection." (PMID 32310998, 2020). "The STAT1−/− mice were infected perorally with 3 × 104 PFU of MNoV and the LJ fucoidan was administered immediately after infection until 4 dpi." (PMID 32906822, 2020). "We detected phosphorylated p38 as early as 30 min post-infection, whereas phosphorylation of the canonical SOCS3-inducer STAT3 as well as STAT1 was observed only after 2 h." (PMID 33023610, 2020). "Innate antiviral defense genes, namely ISGs (e.g., MX1, OAS1, STAT1, STAT2, ISG15), are upregulated early in fatal infection and their expression increases dramatically throughout infection indicative of dysregulated innate immune response." (PMID 32992829, 2020). "We also observed the mRNA expression of STAT1 and IRF8 to be high at 8 dpi upon infection by the RHΔCPSII strain, indicating the probability of activation of STAT1 and IRF8." (PMID 33519775, 2020). "We found that level of STAT1 and STAT2 phosphorylation in IL-36γ pre-treated cells was dramatically decreased at later stages (at 24 h) of infection." (PMID 33193319, 2020). "Within 6 h post-infection, HSV-1 induced both SOCS1/3 expression, which inhibited the phosphorylation of STAT1." (PMID 31861450, 2019). "Infection with MOPV induced comparatively diminished T cell responses in wild-type and in STAT-1-/- mice, predominantly after stimulation with homologous MOPV GPC-derived peptides." (PMID 30650607, 2019). "The innate immune response is crucial during MNV infection; specifically, STAT1 and type I and III interferons (IFNs) play essential roles in combatting infection." (PMID 31213553, 2019). "At the later time point, the infection had minimal if any effect on TNF-α and IL-1β expression in STAT-1-/- and control mice." (PMID 30650607, 2019). "We found that infection with SeV induced the phosphorylation of tyrosine 701 in STAT1 in the lungs of both WT and NKLAM-/- mice beginning at day 3 post-infection." (PMID 31539400, 2019). "Control of infection by acute MNoV strains (e.g., CW3, MNV-1) depends upon the presence of intact type I IFN signaling, as Ifnar1−/− and Stat1−/− mice succumb to lethal infection." (PMID 29361691, 2018). "The expression of MyD88, STAT1, and STAT2 increased after infection with both parasites day 1 and day 4 p.i." (PMID 30327482, 2018). "Although the DNA-binding domain plays a more prominent role in the mounting of an adequate response to IFNβ and control of ex vivo infection, both Stat1−/− models are highly sensitive to corneal HSV-1 infection and succumb by day 8 post-infection." (PMID 30167845, 2018). "Together, our findings revealed a novel regulator of innate immunity, NDR1, which is downregulated by infection with various viruses and regulates IFN signaling by maintaining STAT1 translation." (PMID 30018336, 2018). "The low responders, Ghs6 and M15.2 (respectively), differ especially due to the downregulation of one or more of these genes, STAT1, CCL5, and IRF1, was predicted to increase viral replication and infection in the Ghs6 and M15.2 sublines." (PMID 29535762, 2018).
infection (continued). "In Stat1-/- mice, ZIKV replication took place in the spleen during the early stages of infection resulting in subsequent viremia that was detectable in the blood." (PMID 29668683, 2018). "We observed a persistence of expression of both STAT1 and IRF9 during the chronic phase of infection, albeit at lower levels." (PMID 29324751, 2018). "As IFNα mediates antiviral state through STAT1, we also probed for the ability of this cytokine to block EHDV-TAU infection in LNCaP-JAK1ΔSTAT1 cells." (PMID 29441069, 2018). "The phosphorylation of STAT1 and STAT3 in NKLAM-KO lungs was lower than in WT lungs at 24 hours post-infection." (PMID 29518136, 2018). "STAT1 and STAT2 are key transcription factors activated by type I IFN signaling that are induced following infections with various pathogens including viruses." (PMID 29668683, 2018). "Markedly more infected cells were apparent when STAT1 or IFNAR1 were knocked down, while the control NS cells were resistant to infection similar to unmodified P. leucopus cells." (PMID 28650973, 2017). "Mechanistically, we found infection with both contemporary and ancestral strains of ZIKV blocked phosphorylation of STAT1 and STAT2 downstream of type I IFN signaling in both human DCs and A549 cells." (PMID 28152048, 2017). "By using the phosphorylation of STAT1 at Y701 as a readout for type I IFN signaling, cell extracts were examined 4 h following infection of HeLa cells with HRV16." (PMID 28228588, 2017). "We infected VHS cells with the parental virus or with one of the two mutants, and left the infection for 18 or 40 hours before treating the cells with IFN-α and labelling intracellular phosphorylated STAT1 (STAT1P) for immunofluorescence." (PMID 28475628, 2017). "In STAT1+/+ MEFs, viral titers increased by approximately 2.6-fold for rWSN-GH-NS1-wt between 6 and 36 h post-infection, whereas a marginal 1.5-fold increase in viral titers was observed for rWSN-GH-NS1-Y84F." (PMID 28498306, 2017). "Similar to the observations in Nrf2-silenced cells, HO-1 knockdown resulted in higher levels of the antiviral effectors P-STAT1, STAT1, and RIG-I following VSVΔ51 infection, compared to HO-1-sufficient cells." (PMID 28527723, 2017). "Given the presence of uninfected cells, even at MOI of 1, it remains possible that the STAT1 and STAT2 phosphorylation observed during infection is from uninfected cells." (PMID 28152048, 2017). "The levels of tyrosine-phosphorylated STAT1 and RIG-I were lower at 24, 48 and 72 h post-infection with either the CA/04-NAK331N or CA/04-NAS79L,K331N viruses compared to infection with the parental CA/04 strain or the CA/04-NAS79L viruses." (PMID 28750037, 2017). "While MNV-S99 and MNV-1.CW3 showed comparable growth characteristics in vitro, Stat1 phosphorylation and IFN-β release is strongly decreased after infection with MNV-S99 compared to MNV-1.CW3." (PMID 27294868, 2016). "JAK1, STAT1, and STAT3 expression levels were dramatically elevated in infection groups of both db/db and C57 mice." (PMID 27995146, 2016). "The systems biology analysis identified multiple immune system and inflammation molecules (e.g., STAT3, STAT1, CEBPB, JUN, IGF1, SPP1, NFKB2, IL-1β, and CSF1) as master regulators that are activated upon infection." (PMID 26865111, 2016). "In order to activate transcriptional factors involved in innate immune responses, HeLa cells were pre-treated with recombinant human IFN-α, which activates STAT1, STAT2, and IRF9, followed by infection with WT-Ad." (PMID 26814140, 2016). "Phosphorylated and total levels of STAT1 and IRF3 were quantitated at 24 hours post-infection by immunoblot." (PMID 27505057, 2016). "β6 KO mTEC exhibited significant increases in total STAT1 and IRF3 levels as compared to WT mTEC after infection as well as at baseline, although differences in phosphorylated STAT1 and IRF3 were minimal." (PMID 27505057, 2016).